TSLP (thymic stromal lymphopoietin)
Diseases named in the same sentence as TSLP in open-access papers (continued):
Sharing a sentence is not in itself a finding about the gene and the disease.
infection (continued). "To determine the role of TSLP during RSV-induced ILC2 activation, we assayed the total number of ILCs and IL-13+ ILC2s in TSLPR KO mice at day 4 after infection." (PMID 27156176, 2016). "Thymic stromal lymphopoietin (TSLP), an epithelial derived cytokine that can be produced in the infected lung, promotes expansion of the CD8+ T cells at the site of infection directly and indirectly via CD11b+ inflammatory DCs." (PMID 25071780, 2014). "In contrast, SG3PDH/PRX-MAP combined with the type 2 cytokines, thymic stromal lymphopoietin (TSLP), IL-25, and IL-33, switched the antigen specific response elicited during a challenge infection towards a Th2 phenotype." (PMID 24465551, 2014). "While this would suggest that TSLP action on dendritic cells is a means for generating type two immunity against Tm infection, DC detection of TSLP was not here demonstrated." (PMID 40944312, 2025). "In cultured NHBE and HBECs but not HNEpCs or Caco-2 cells, TSLP levels were significantly elevated after 24 h post-infection with SARS-CoV-2 (p < 0.001) in a dose-dependent manner." (PMID 36851770, 2023). "Activated ILC2s produce copious amounts of type-2 cytokines (e.g. interleukin-5 (IL-5) and IL-13) which respond to non-specific alarmins such as IL-25, IL-33, and thymic stromal lymphopoietin (TSLP) under infection or insults." (PMID 37833706, 2023). "Thus, while TSLP appears to have variable direct effects on primary CD8+ T cell responses, possibly depending on the context of infection, here we reveal that TSLP differentially affects naïve and memory cell homeostasis." (PMID 33439121, 2021). "Our results showed that BUD significantly inhibited poly I:C-induced TSLP expression whether added before or after poly I:C exposure, and similar effects were also observed in response to HRV16 infection." (PMID 32120846, 2020). "This study suggests that anti‐TSLP failed to inhibit neutrophil infiltration or induce normal production of proinflammatory cytokines to control infection in the septic mouse." (PMID 31628890, 2019). "Infection with influenza virus, rhinovirus, and respiratory syncytial virus (RSV) can all result in ILC2-mediated airway hyperreactivity and inflammation via IL-33 and TSLP production." (PMID 30893756, 2019). "We report a strong induction of numerous pro-inflammatory cytokines, chemokines and AMPs such as CXCL1, CXCL2, CXCL5, CXCL8, CCL20, TNFα, TSLP, IL-23α, IL-32, IL-6, hBD2 and S100A7 during the infection of monolayered primary keratinocytes and reconstructed epidermis with the wild-type PAK strain." (PMID 30070169, 2018). "Moreover, previous studies have shown that infections with RSV strains A2 and Line 19 provoke TSLP expression in murine lungs, although these studies focused on the effect of TSLP on dendritic cells and TH2 cells." (PMID 27156176, 2016). "IECs have been shown to differentiate into goblet cells following infection with T. muris in response to TH2 cell-derived cytokines and produce effector molecules such as the mucins Muc5AC and Muc2, cytokines such as TSLP as well as the small protein RELMβ." (PMID 27598373, 2016). "Measurements of TSLP levels by using ELISA between 24 and 96 hours after infection were all less than the limit of detection (data not shown)." (PMID 27156176, 2016). "ILC2s in both humans and mice secrete TH2-type cytokines IL-4, IL-5, and/or IL-13 in response to IL-9, IL-25, IL-33, and thymic stromal lymphopoietin (TSLP), as well as during pulmonary inflammation or infection with Nippostrongylus brasiliensis, a helminth controlled by TH2-type cytokine responses." (PMID 26322047, 2015). "Interestingly, PAR-2 (mRNA), which is believed to be important in fungal (Alternaria) extract-mediated TSLP induction, is inhibited in a TLR4-dependent manner by A. fumigatus-infection in immunocompromised mice." (PMID 24063011, 2013).
infection (continued). "This implies that TSLP is not likely to beimportant in conditioning the dermal immune response in our multiple infection model butdoes not rule out other cytokines such as IL-25 or IL-33 recently described to beimportant for Th2 induction." (PMID 21445234, 2011). "IL-33 could act alone or in concert with other mediators, such as thymic stromal lymphopoietin (TSLP), which is also expressed by inflamed skin and tonsillar crypt epithelium, and can be released by epithelial cells in response to trauma or infection." (PMID 18836528, 2008). "Potential epithelial production and DC detection of TSLP has been explored, but upregulation of Tslp by epithelial cells in response to infection, or expression in the caecal epithelium in vivo has not yet been demonstrated; neither has significant expression of the TSLPR by DCs been evidenced." (PMID 40944312, 2025). "The release and function of TSLP by dermal TRMs during L. major infection appears to be non-redundant, as neither IL-33 nor IL-25 transcripts were detected in the dermal TRM cluster, and mice deficient in these cytokines did not alter their infection outcome." (PMID 38030609, 2023). "Compared to RV-A (RV-1B) infection, RV-C (RV-C15) infection induced higher BALF eosinophilia, mRNA expression of IL-5, IL-13, IL-25, Muc5ac and Gob5/Clca, protein production of IL-5, IL-13, IL-25, IL-33 and TSLP, and expansion of ILC2 in naive and HDM-immunized BALB/c mice." (PMID 35386658, 2022). "Kennedy and colleagues, observed an increase in TSLP gene expression and protein as well as gene expression of IL-25 and IL-33, in asthmatic donor lungs compared to non-asthmatic controls following RV-A39 infection." (PMID 34912343, 2021). "Importantly, unlike male mice, females were not exacerbated following RSV-infection alone and thus were independent of TSLP, supporting a sex-specific role for this pathway." (PMID 31076663, 2019). "Furthermore, endocervical epithelial cells were demonstrated to secrete thymic stromal lymphopoietin (TSLP) in vitro, resulting in the activation of mDC that subsequently produce CCL17 and CCL22, further attracting naive CD4+ T-cells for expansion and infection." (PMID 29415518, 2018). "For example, IL1-β (gene IL1B) and IL23, which were markedly induced by Mtb in our infection model, are known to induce group 3 ILC (ILC3); IL15 among others activates ILC1 cells, and IL1-β, thymic stromal lymphopoietin (TSLP) and IL33 are prominent activators of ILC2 cells." (PMID 29977236, 2018). "Recently, it has been reported that the infection of hepatocytes in vitro by HCV results in a remarkable production of TSLP through a mechanism regulated in a nuclear factor-κB-dependent fashion, and that TSLP is able to enhance the release of T-helper 17 differentiating cytokines by DCs." (PMID 25889007, 2015). "In support of this result, no TSLP protein was detected in L-HMVEC secretomes that were harvested in both the acute and persistent phase of infection." (PMID 32486193, 2020). "Within the first 5 days of infection, the absolute numbers of ILC2 did not significantly change in the dermis, which is in line with the unaltered expression of cytokines activating (IL-18, IL-25, IL-33, TSLP) or inhibiting ILC2 (IL-27, IFN-γ)." (PMID 35894051, 2022). "Infection with SA-induced or PA-induced high production of IL-1β, IL-23, and TGF-β in nasal epithelial cells, whereas no IL-33 or TSLP could be detected." (PMID 31089134, 2019). "Moreover, studies using A549 cells co-transfected with the human TSLP promoter with a reporter, and a dominant-negative form of RIG-I (DN-RIG-I), showed that hRSV-infection could induce activation of this pathway to increase TSLP expression." (PMID 30936869, 2019).
cancer (84 papers, 2011 to 2025). A tumor composed of atypical neoplastic, often pleomorphic cells that invade other tissues. "Increasing evidence suggests that TSLP is also closely associated with the development of autoimmune diseases and cancers." (PMID 40787610, 2025). "Some of the other cells expressing TSLP, include mast cells, smooth muscle cells, cancer-associated fibroblasts, dendritic cells (DCs), and trophoblasts." (PMID 40787610, 2025). "The basophils in TDLNs were observed, and the role of cancer-associated fibroblasts in releasing TSLP was noted, which in turn activated dendritic cells (DCs) to generate IL-3 from CD4* T cells." (PMID 39816393, 2024). "Th2 cells are differentiated by dendritic cells endowed with Th2-polarizing capability by the thymic stromal lymphopoietin (TSLP) that is secreted by IL-1-activated cancer-associated fibroblasts (CAFs)." (PMID 39125655, 2024). "Together, these findings provide evidence that TSLP induction to drive CD4+ T cell activation can potentially be an effective therapeutic strategy to prevent cancer development and progression in high-risk patients." (PMID 36467403, 2022). "TSLP has been implicated in the induction and progression of several experimental and human cancers." (PMID 34440780, 2021). "Thymic stromal lymphopoietin (TSLP) is an IL-7-like cytokine that has been reported to be associated with several malignant tumors." (PMID 31023965, 2019). "TSLP gene polymorphisms have been associated with increased susceptibility to cancer progression in different organs." (PMID 31210014, 2019). "Various cell types can produce TSLP: endothelial, epithelial cells and epidermal keratinocytes, airway smooth muscle cells, fibroblasts, DC, trophoblasts, and cancer or cancer-associated cells." (PMID 22876248, 2012). "In addition, in PDA orthotopically injected mice, IL-1R antagonist inhibited the secretion of thymic stromal lymphopoietin (TLP) by cancer-associated fibroblasts." (PMID 39176093, 2024). "Moreover, intratumor Th2-type cell infiltrates were correlated with cancer-associated fibroblast TSLP production and reduced survival in pancreatic cancer." (PMID 38557942, 2024). "Thus, TSLP has been associated with both promoting and attenuating the severity of cancer in a range of malignancies, suggesting context‐dependent effects for this cytokine in malignant disease." (PMID 37165746, 2023). "At the same time, periostin production by cancer-associated fibroblasts (CAFs) and subsequent induction of thymic stromal lymphopoietin (TSLP) synthesis by keratinocytes create a positive feedback loop for continuous immunomodulation of the skin microenvironment." (PMID 37190290, 2023). "Thymic stromal lymphopoietin (TSLP) emerges as a cytokine with pleiotropic properties, which is not only involved in various allergic disorders, but is also implicated in chronic inflammatory diseases and cancers." (PMID 35216130, 2022). "Moreover, the deficiency of TSLP in cancer cells alone can efficiently abrogate cancer progression and lung metastasis." (PMID 31023965, 2019). "Experiments conducted on TSLP receptor-deficient mice indicated that TSLP might play an essential role in protection and metastasis of cancer cells through its receptor on CD4+T cells." (PMID 31023965, 2019). "Thymic stromal lymphopoietin is expressed mainly by epithelial cells and epidermal keratinocytes; other types of cells, such as mast cells, smooth muscle cells, fibroblasts, dendritic cells, trophoblasts, and cancer or cancer-associated cells also express TSLP." (PMID 27826297, 2016). "In addition, Th2 cells were correlated with cancer-associated fibroblast thymic stromal lymphopoietin and a high abundance of them could reduce survival in PAAD." (PMID 35046996, 2021). "However, TSLP can be produced also by airway smooth muscle cells, human DCs and mast cells, human monocytes, macrophages and granulocytes, synovial and cancer-associated fibroblasts (CAF), murine basophils, and cancer cells." (PMID 30057581, 2018).
cancer (continued). "Since then, several experimental and clinical studies have shed light on the different mechanisms of the protumorigenic role of TSLP and its isoforms in cancer." (PMID 40873585, 2025). "Previous clinical and experimental studies concluded that the role of TSLP-TSLPR axis in cancer was controversial." (PMID 40873585, 2025). "These intriguing results emphasize the need for further studies to investigate the expression and role(s) of the two TSLP isoforms in human cancers." (PMID 40873585, 2025). "In this Review, we will highlight recent advances in TSLP immunobiology in the context of human and experimental cancers." (PMID 40873585, 2025). "Previous research has largely overlooked the application of analytical methods to investigate the differential expression patterns and roles of the two distinct isoforms of TSLP in different cancers." (PMID 40873585, 2025). "In this Review, we will summarize the work on TSLP immunobiology, emerging data regarding TSLP isoforms and a new-found role for TSLP in a wide variety of cancers." (PMID 40873585, 2025). "The role of TSLP in human and experimental cancers has been the focus of several studies, with somewhat contradictory findings." (PMID 40873585, 2025). "TSLP is predominantly expressed by epithelial cells and keratinocytes but can also be produced by several immune cells and some cancers." (PMID 40873585, 2025). "It is now widely acknowledged that TSLP has a role in the development of pathological disorders, including cancer, host defence, allergy disease, and chronic inflammatory disease." (PMID 39057040, 2024). "Th2 cells are “driven” by OX40 ligand (L)-expressing dendritic cells in response to cancer-derived thymic stromal lymphopoietin (TSLP)." (PMID 38473274, 2024). "TSLP, a cytokine produced in response to environmental and inflammatory stimuli, is involved in inflammatory diseases and cancer." (PMID 37660072, 2023). "Thymic stromal lymphopoietin (TSLP) is well known for its association with type 2 immunity at the barrier surface, allergic conditions, chronic inflammatory diseases, and cancer." (PMID 37809094, 2023). "Indeterminately, in certain studies, TSLP has a cancer-promoting effect, whereas in others, a cancer-protective effect." (PMID 36437960, 2022). "To further examine the mechanism of TSLP-mediated cancer suppression in the lung, we stained the Tslptg KrasG12D and KrasG12D lungs with TUNEL (a marker for cell death) and Ki67 (a marker for cell proliferation)." (PMID 35565302, 2022). "Thymic stromal lymphopoietin (TSLP), long known to be involved in Th2 response, is also implicated in multiple inflammatory dermatoses and cancers." (PMID 36046760, 2022). "Other studies have shown that TSLP can act to facilitate cancer development by suppressing the immune response." (PMID 36467403, 2022). "Overexpressed thymic stromal lymphopoietin (TSLP) and tyrosine kinase 2 (TYK2) was also associated with worse survival through pan-cancer analysis." (PMID 35874683, 2022). "We and others have reported that cancers use TSLP and G-CSF to mobilize BM pre-B cells and HSPS in circulation." (PMID 36104343, 2022). "The role of TSLP in cancer is rather controversial, although in the majority of tumors it plays a protumorigenic role." (PMID 34440780, 2021). "Thymic stromal lymphopoietin (TSLP) has been demonstrated to drive immune cell polarization into the cancer-promoting Th2 immunophenotype in a variety of tumors." (PMID 35069599, 2021). "Future studies should go deeper inside the biochemical and immunological mechanisms of formation of different TSLP isoforms and their multifaceted roles in cancer and in chronic inflammatory disorders." (PMID 34440780, 2021). "The immunomodulatory roles of TSLP in inflammation and cancer pathogenesis mentioned previously have become an interest for many researchers and pharmaceutical companies." (PMID 34306760, 2021).
cancer (continued). "In the 4T1 orthotopic murine model TSLP was produced by cancer cells that directly acted on TSLPR-expressing CD4+ T cells to induce their Th2 differentiation." (PMID 33042121, 2020). "More recently, a role for TSLP has been also reported in chronic inflammatory and autoimmune disorders and in cancer." (PMID 33042121, 2020). "Here we report and discuss the Th2-dependent and Th2-independent roles of TSLP in cancer and possible therapeutic targeting." (PMID 33042121, 2020). "TSLP secreted by cancer cells promotes the development and metastasis of cancer by inducing the expression of vascular endothelial growth factor (VEGF)." (PMID 31885639, 2019). "In conclusion, this is the first study revealing the correlation of TSLP overexpression in EOC patients with cancer progression and shorter survival time." (PMID 31023965, 2019). "Thymic stromal Lymphopoeitin (TSLP) is a key cytokine involved in inflammation and cancer progression." (PMID 31210014, 2019). "The study suggests that TSLP plays an important role in cancer cell, and the inactivation of TSLP almost completely eliminates cancer progression and lung metastasis." (PMID 31885639, 2019). "In mouse models of breast and pancreatic carcinogenesis, it was found that early administration of TSLP blocked cancer development." (PMID 30057581, 2018). "The mechanisms regulating TSLP expression and secretion from cancer cells, including a potential link with oncogenic events, remain to be established." (PMID 30214685, 2018). "Together with our data, these results highlighted the context-dependence of TSLP signaling in cancer." (PMID 26919238, 2016). "The increasing interest in the role of TSLP in cancer has focused on the immune-regulatory effect of TSLP on different immune cells." (PMID 26919238, 2016). "TSLP was detected in situ in cancer cells and plasma levels were correlated with poor prognosis." (PMID 40873585, 2025). "TSLP induced VEGF-A release from cancer resident macrophages." (PMID 40873585, 2025). "Importantly, ILC2-activating signals, including IL-33, IL-25, and thymic stromal lymphopoietin (TSLP), also contribute to the development of an immunosuppressive microenvironment in different types of cancer." (PMID 40247153, 2025). "In addition to its role in barrier immunity, recent studies have a role for TSLP in cancer development." (PMID 40873585, 2025). "TSLP’s immunomodulatory roles extend to inflammation and cancer." (PMID 38539468, 2024). "Indeed, the high expression of thymic stromal lymphopoietin (TSLP) in cancer cells correlates with a poor prognosis for CRC patients." (PMID 38033043, 2023). "However, the impact of TSLP induction on advanced cancer with altered cellular phenotypes is unclear." (PMID 36467403, 2022). "It was gradually revealed that TSLP is extensively involved in autoimmune diseases and cancers." (PMID 36046760, 2022). "TSLP is a widely studied cytokine with various roles in different cancers." (PMID 35558081, 2022). "Moreover, TSLP has been controversially reported to play either a protumor or an antitumor role in various cancer types (reviewed in ref .11)." (PMID 36107619, 2022). "TSLP and Th2 cells are found to play complex roles in cancer." (PMID 36467403, 2022). "Importantly, most cancer-protective effects of TSLP/Th2 cells have been discovered in the context of early carcinogenesis using spontaneous cancer models." (PMID 36467403, 2022). "Earlier studies on the crosstalk between CAFs and DCs in different cancer models suggest that CAF-mediated immunoregulation on DCs is achieved via release of the cytokine thymic stromal lymphopoietin (TSLP) or expression of the catalytic enzyme tryptophan 2,3 dioxygenase (TDO2)." (PMID 34177901, 2021). "A novel and unexpected function of TSLP has been demonstrated in experimental and human cancers." (PMID 34440780, 2021).